LOX (lysyl oxidase)
Diseases named in the same sentence as LOX in open-access papers (continued):
Sharing a sentence is not in itself a finding about the gene and the disease.
tumor (continued). "Our results demonstrate to our best knowledge for the first time that LOX is secreted from tumor cells also in response to irradiation and indicate a differential regulation of LOX-expression and secretion in response to IR and hypoxia." (PMID 25052686, 2014). "We here demonstrate that irradiation of tumor cells will also lead to increased amounts of secreted LOX, however in a gene transcription- and hypoxia-independent way." (PMID 25052686, 2014). "Recently, high levels of LOX have been detected in some tumors under hypoxia conditions facilitating tumor metastasis." (PMID 25546273, 2014). "Here we show that LOX expression is reduced in lymph node metastases compared to matched primary tumour samples from the same patients." (PMID 25141126, 2014). "With the exception of MDA-MB-231 cells, all tumor cell lines studied demonstrated enhanced LOX secretion in response to IR, but to different magnitudes depending on the cell type." (PMID 25052686, 2014). "To further understand mechanisms for NNK carcinogenicity, we have examined NNK effects on the expression of LOX, a tumor suppressor gene." (PMID 25546273, 2014). "Transwell migration assays were performed to evaluate invasive capacity of naïve tumor cells in response to IR-induced LOX." (PMID 25052686, 2014). "LOX has been shown to enhance tumor cell proliferation and invasion and its expression is correlated with poor clinical outcome." (PMID 25174950, 2014). "Mechanistically, LOX secreted by hypoxic tumor cells colocalizes with fibronectin at sites of future metastases and crosslinks collagen in the basement membrane, thereby permitting BMDC cell recruitment." (PMID 25238333, 2014). "We demonstrate that clinically relevant doses of IR enhance LOX secretion in vitro and in vivo and that IR-induced LOX stimulates tumor cell invasion on a functional level." (PMID 25052686, 2014). "Regardless of its mechanism, it will be important to investigate the functional effect of IR-enhanced LOX levels in the blood on tumor cell dissemination and premetastatic niches." (PMID 25052686, 2014). "In view of LOX tumor suppressor activity and other biological functions, down-regulation of LOX by NNK is deeply involved in NNK pathogenesis and carcinogenesis." (PMID 25546273, 2014). "LOX has both intracellular and extracellular functions, and the tumour suppressive activity appears to be predominantly due to its intracellular functions, particularly the modulation of gene expression." (PMID 25141126, 2014). "A large, prospective, multicenter study is needed to demonstrate the predictive value of LOX in GC metastasis in combination with other tumor markers." (PMID 25060181, 2014). "Next, we also determined the level of human,tumor-derived LOX in the serum of tumor xenografted mice, which were irradiated with the two treatment regimens." (PMID 25052686, 2014). "Here, we investigated the effects of IR on the expression and secretion of lysyl oxidase (LOX) from tumor cells." (PMID 25052686, 2014). "LOX, secreted by prominent central hypoxic tumor cells, can crosslink collagens and elastin, thereby increasing insoluble matrix deposition and tissue stiffness." (PMID 24338768, 2014). "Clinicopathological analysis showed that both LOX and HIF-1α expression are significantly associated with tumor FIGO classification (p=0.035 and p=0.032), tumor size (p=0.033 and p=0.032) and lymph node metastasis (p=0.016 and p=0.028, respectively)." (PMID 23545606, 2013). "By contrast, the C-terminal domain of LOX, which contains the enzymatic activity, had the opposite effects, corroborating that the tumor suppressor activity of LOX is mediated exclusively by its propeptide domain." (PMID 23750284, 2013). "Increased LOX expression was significantly correlated with the depth of tumor invasion, lymph node status and TNM stage (P<0.05)." (PMID 23425977, 2013).
tumor (continued). "Tumour-stromal interactions change under hypoxic conditions to promote tumour progression via the activity of enzymes such as LOX, angiogenic factors and infiltrating macrophages." (PMID 24286369, 2013). "Our results revealed significant correlations between the upregulated expression of LOX and the depth of tumor invasion, lymph node status and TNM stage." (PMID 23425977, 2013). "To elucidate the mechanisms underlying induction of stellate morphology, we examined the expression of three tumor-promoting genes, namely Myc, LOX, and plasminogen activator inhibitor-1 (PAI-1) because of their established link to TGF-β1 and Col-1." (PMID 23409704, 2013). "LOX has been intensively studied in cancers as its importance in tumor progression becomes more thoroughly realized." (PMID 23545606, 2013). "This indicates that hypoxia-induced LOX and HIFs are important factors that regulate tumor microenvironments to favor metastasis." (PMID 24179495, 2013). "The first evidence about the tumor suppressor activity of LOX came from studies addressed to identify the genes involved in the IFN-γ mediated-reversion of ras-transformed malignant cells." (PMID 23750284, 2013). "In our study, we also found that LOX protein expression was significantly correlated with depth of tumor invasion, lymph nodes status, and TNM stage." (PMID 23425977, 2013). "The role of the propeptide has been, however, much less studied, although recent reports suggest that LOX propeptide acts as a tumor suppressor in several contexts." (PMID 23750284, 2013). "Subsequently, we performed xenograft experiments to analyse the effect of LOX-PP on tumor growth in vivo." (PMID 23750284, 2013). "In the Cox multiple regression analysis, depth of tumor invasion, histological differentiation, lymph node status and LOX expression independently significantly affected survival." (PMID 23425977, 2013). "As a component of the extracellular matrix, LOX plays a role in facilitating tumor-stromal interactions that are important for tumor progression and metastasis." (PMID 23425977, 2013). "Tumour-secreted factors such as VEGF-A, PlGF, TGF, TNF-a and LOX have been shown to play active roles in the recruitment of bone marrow (BM)-derived cells to the primary tumour microenvironment and pre-metastatic niches." (PMID 26082317, 2013). "In contrast to active LOX, the LOX propeptide (LOX-PP) generated during the course of BMP-1-mediated LOX activation in the ECM acts as a tumor suppressor through multiple signaling pathways." (PMID 24265769, 2013). "LOX also acts as a critical mobilizing factor, which recruits CD11b+ myeloid cells to form the niche to facilitate the colonization of metastatic tumor cells." (PMID 24216979, 2013). "The niche-promoting effects of LOX include cross-linking of collagen IV that recruits first myeloid cells and then bone-marrow-derived cells and tumor cells." (PMID 22509805, 2012). "Further, lysyl oxidase-induced crosslinking of collagen leads to stiffening of the tumor stroma and induces tumor progression." (PMID 23251159, 2012). "The MDA-MB-231 is therefore the natural model to investigate if a combinatorial therapy targeting ACSL4, COX and LOX is effective in reducing tumor growth." (PMID 22808264, 2012). "Ectopic LOX gene expression reduced colony formation of cultured gastric cancer cells and tumor formation in a xenograft model." (PMID 22438909, 2012). "Tumor suppressor as well as metastasis promoting functions of LOX have been described in several cancer types." (PMID 23213280, 2012). "The logical next step was to analyze the effect of ACSL4, COX-2 and LOX inhibitors on tumor growth in vivo." (PMID 22808264, 2012). "As this finding was unexpected, the validity of the results in the murine tumor was confirmed by a different LOX qPCR assay." (PMID 21306648, 2011). "Among tested genes, our study identified CA9, GLUT1 and possibly LOX as highly specific biomarkers of tumor hypoxia in vivo." (PMID 21306648, 2011).
tumor (continued). "Similar results were recently reported for the metastasis-associated gene lysyl oxidase (LOX), whose expression was associated both with tumor suppression and tumor progression depending on transformation status." (PMID 21408220, 2011). "Among five CpG loci whose methylation was significantly associated (Q<0.05) with lymph node status, four (two in COL1A2, and one each in LOX and P2RX7) were also associated with tumor size (Q<0.05)." (PMID 20686660, 2010). "The tumor suppressor function of LOX was initially demonstrated in ras-transformed fibroblasts, lacking LOX transcription and activity." (PMID 21139993, 2010). "Perhaps LOX activity, in combination with other factors released by osteoblasts, hypertrophic chondrocytes, and/or stromal cells promotes tumor cell chemo-attraction, motility, proliferation, and survival at these skeletal sites." (PMID 19440335, 2009). "Within this context, lysyl oxidase (LOX) is thought to play an important role in modulating tumor behavior." (PMID 19440335, 2009). "The findings that LOX activity is modulated by oxygen levels, and also that LOX is able to regulate cell migration and adhesion, have generated considerable interest in the role of LOX during tumor progression." (PMID 19440335, 2009). "Other recent studies showed that LOX [GenBank:NM_002317] expression correlates positively with tumor progression and co-localization with hypoxic regions (defined by hypoxia inducible factor-1α expression) in DCIS and IDC primary tumors." (PMID 18928525, 2008). "LOX inhibitor-mediated reduction of matrix stiffness has been shown to significantly enhance T cell tumor infiltration and migratory capacity, while synergistically potentiating the anti-tumor efficacy of PD-1/PD-L1 blockade therapy." (PMID 41362727, 2026). "The model of the whole‐tumor region has a good predicting effect in LOX expression, with the area under the receiver operating characteristic (ROC) curve being 0.775 in the training set, while the average under the curve (AUC) value of the 5‐fold cross‐validation was 0.754." (PMID 40792413, 2025). "Comprehending the mechanisms of LOX can offer valuable perspectives on tumor biology." (PMID 40661776, 2025). "Additionally, tumor-secreted factors such as lysyl oxidase (LOX) initiate ECM remodeling via collagen crosslinking and monocyte recruitment, enhancing niche readiness." (PMID 40658744, 2025). "Furthermore, pharmacological inhibition of LOX significantly reduced tumor cell migration and enhanced apoptosis, both in vitro and in vivo." (PMID 40940809, 2025). "Emerging evidence suggests that LOX activity may contribute to tumor progression and metastasis by facilitating ECM remodeling, promoting cancer cell invasion, and enhancing angiogenesis." (PMID 40661776, 2025). "Furthermore, the activity of enzymes such as LOX not only enhances the cross-linking of collagen fibers but also promotes the colonization and growth of tumor cells in distant organs by activating related signaling pathways." (PMID 40211368, 2025). "Furthermore, LOX proteins are known to interact with other components of the tumor microenvironment, including immune cells, further complicating their role in cancer progression." (PMID 40661776, 2025). "Interestingly, adipocytes within the tumor stroma release MMPs (-2, -3, -7, and -9) and lysyl oxidase (LOX), which significantly modify and degrade the ECM, creating migration pathways for cancer cells." (PMID 41369383, 2025). "Furthermore, increased LOX expression induces matrix crosslinking and stiffness, promoting tumor growth and metastasis in mice injected with HR+-derived organoids." (PMID 40847127, 2025). "LOX is an enzyme involved in the enzymatic crosslinking of collagen and is generally expressed in higher quantities in tumor matrices, contributing to the stiffening of the tumor substrate." (PMID 41149224, 2025). "Importantly, LOX inhibition synergized with Sorafenib, reducing tumor volume compared to sorafenib monotherapy." (PMID 40685383, 2025).
tumor (continued). "The expression of LOX in tumor tissue significantly correlated with overall survival (OS)." (PMID 40792413, 2025). "Considering the roles of integrins and LOX in matrix stiffness, it has been reported that resistance may develop due to the difficulty of chemotherapy agents reaching the tumor." (PMID 39857068, 2025). "It is hypothesized that hypoxia and MelCAM may mediate tumor cell migration for triple-negative BC via the regulation of specific secreted factors (such as LOX, MMPs) by CAF-S4." (PMID 40869109, 2025). "Fibroblast-derived LOX—abundant in iCCA stroma—increases tumor OXPHOS and stemness, linking matrix cross-linking to metabolic hard-wiring and aggressive behavior; pharmacologic LOX inhibition remodels the fibro-inflammatory stroma and sensitizes CCA to therapy in preclinical studies." (PMID 41394868, 2025). "Interestingly, lysyl oxidase (LOX), a protein associated with tumor progression, was reduced in U87COX-2KO and MG cells." (PMID 40649978, 2025). "The radiomic model of the whole‐tumor region has a good predicting effect in the expression of LOX." (PMID 40792413, 2025). "LOX was involved in the regulation of immune response and tumor invasion and metastasis." (PMID 40792413, 2025). "Tumour samples were submitted to immunohistochemistry to detect LOX and LOXL2." (PMID 41408914, 2025). "For example, inhibiting LOX can decrease tumor cell invasiveness, thereby slowing metastasis." (PMID 40406488, 2025). "In this respect, ATOX1 plays an important role in vascular remodeling by promoting copper- and RAS-related C3 botulinum toxin substrate 1 (RAC1)-dependent migration of vascular smooth muscle cells, macrophage infiltration and LOX activation, thereby contributing to tumor angiogenesis." (PMID 40721800, 2025). "Furthermore, LOX increases matrix stiffness through its collagen crosslinking activity, which directly influences cellular behavior and leads to tumor cell proliferation." (PMID 39682261, 2024). "LOX plays an important role in tumor formation and the proliferation and migration of tumor cells." (PMID 39539438, 2024). "Interestingly, there were different expression patterns in the other areas, as CP as well as IGFBP2 were expressed more toward the cellular part of the tumor, whereas LOX was expressed more in the peripheral vascular zones." (PMID 38339384, 2024). "In the cancer literature, LOX has been shown to drive metastasis and tumor growth." (PMID 39766266, 2024). "All 5 LOX isoforms have been shown to promote oncogenesis in solid tumors through various mechanisms, such as increasing stromal density, facilitating immune evasion, as well as augmenting tumor growth and metastatic spread." (PMID 39101793, 2024). "The shortest OS was observed in patients with high LOX+ Fibroblasts and M2 Macrophages, suggesting these two cell types could work synergistically to precipitate tumor development." (PMID 39251966, 2024). "The data suggest that adipocyte-secreted LOX changes the mesenchymal phenotype of BC cells in a manner that could promote secondary tumour formation, particularly at sites high in adipocytes such as the bone marrow." (PMID 38468823, 2024). "Inhibitors of LOX enzymatic activity such as beta-aminopropionitrile (BAPN) were tested in combination with PD-1 treatment in mouse models leading to tumor reduction and increased T-cell infiltration, however the clinical use of BAPN is impeded by concerns regarding toxicities." (PMID 38659022, 2024). "Furthermore, two cell subtypes, LOX+ Fibroblasts and M2 Macrophages, were enriched in tumor tissue and related to the outcome of GC patients." (PMID 39251966, 2024). "Since damage-associated molecular patterns associated with immunogenic cell death CD were significantly elevated in URCCA4.3 tumors treated with combination therapy, we also investigated the dynamics of the tumor immune microenvironment in response to pan-LOX inhibition." (PMID 39101793, 2024).
tumor (continued). "Hypoxia characterizes the tumor microenvironment and is associated with modulating angiogenesis, vasculogenesis, and cancer progression by triggering factor production in stromal cells like VEGF or lysyl oxidase (LOX)." (PMID 38231464, 2024). "As a result, we hypothesize that LOX+ Fibroblasts and monocyte/macrophages interact in hypoxic regions, possibly influencing tumor progression." (PMID 39251966, 2024). "In tumor-derived LOX+ Fibroblasts, the epithelial-mesenchymal transition was also upregulated." (PMID 39251966, 2024). "For instance, LOX secretions from cancer cells are capable of remodeling local environments, where it creates permissive niches (premetastatic niches) for tumour cells to subsequently colonize and form overt secondary tumours." (PMID 38468823, 2024). "Similarly, the cuproenzyme lysyl oxidase (LOX) has been found to promote tumor cell invasion and metastasis." (PMID 38918694, 2024). "A recent study revealed that stromal CAFs accumulate at the invasive front of PTC tumours, where the deposition of collagen (Col1) and the expression of lysyl oxidase (LOX) enzymes were also detected, confirming the significant association between these factors." (PMID 39187514, 2024). "Moreover, LOX released by hypoxic tumor cells at the primary site can induce collagen crosslinking at distant pre-metastatic niches, thereby contributing to the establishment and maintenance of these niches." (PMID 39682261, 2024). "Notably, LOX+ Fibroblasts were significantly enriched in hypoxia-related pathways, indicating that the tumor’s hypoxic environment interacts with LOX+ Fibroblasts." (PMID 39251966, 2024). "Furthermore, two cell subtypes, LOX+ Fibroblasts and M2 Macrophages, were enriched in tumor tissue and related to the survival of GC patients." (PMID 39251966, 2024). "ATP7A may suppress tumor cell growth and migration by inhibiting the activity of LOX.ATP7A may promote angiogenesis by combining with VEGFR2.ATP7A or ATP7B can bind to platinum drugs to expel it from cancer cells, producing chemotherapy drug resistance." (PMID 36925927, 2023). "Therefore, it is possible that LOX and Arg LOX-PP play opposing effects in tumor development and metastasis by this or another still unexplored mechanism." (PMID 37298359, 2023). "In addition to tumor cells, activated fibroblasts also represent a source of LOX in the pre-metastatic tissue." (PMID 37350937, 2023). "Secretion of LOX by tumor cells leads to cross linking of collagen and elastin and this highly crosslinked collagen matrix contributes to the extensive tumor rigidity and reduced oxygen supply to tumor." (PMID 38022679, 2023). "The theory of primary CSCs is that CSCs undergo symmetric or asymmetric division, are capable of regenerating the entire tumor mass after chemo/radiotherapy, and lead to recurrence and metastasis (particularly through activation of lysine oxidase (LOX) in a hypoxic environment)." (PMID 37240338, 2023). "The cuproenzyme LOX is involved in the invasion and metastasis of tumor cells." (PMID 37600770, 2023). "We hypothesized that a pan-lysyl oxidase inhibitor would improve outcome when used in combination with chemotherapy, through blunting the development of tumor desmoplasia." (PMID 37640930, 2023). "Thus, LOX and LOXs, which mediates collagen crosslink in tumor cell, are optimal targets to alleviate ECM stiffness." (PMID 36906534, 2023). "Lipoxin (LX), a lipid mediator of LOX, can inhibit tumor cell growth." (PMID 37004014, 2023). "Moreover, primary tumor resection develops hypoxic areas that are a source of LOX, which enters the circulation and ultimately reaches to the lungs, resulting in a stiffer environment that promotes lung metastasis through FAK activation." (PMID 37468874, 2023).